VIM (vimentin)
Diseases named in the same sentence as VIM in open-access papers (continued):
Sharing a sentence is not in itself a finding about the gene and the disease.
pancreatic cancer (continued). "Mechanistically, rfhSP-D downregulates the EMT-related gene signatures (Vimentin, Zeb1, and Snail), and hence, pancreatic cancer cells invasion, mainly by attenuating TGF-β signaling pathway." (PMID 30158928, 2018). "Aberrant activation of EMT has been attributed to over-expression of mesenchymal markers, such as Zeb1 (zinc finger E-box binding homeobox 1), Snail, and Vimentin, as well as repression of E-cadherin, an epithelial marker in the pancreatic cancer cells." (PMID 30158928, 2018). "Dysregulation of the vimentin filament network can have consequences on pancreatic chemosensitivity, as vimentin is an active factor in the epithelial-to-mesenchymal transition that grants pancreatic tumors high chemoresistance." (PMID 31867128, 2018). "We additionally evaluated the EMT marker genes, E-cadherin and vimentin, with two pancreatic cancer cell lines, SMAD4-intact SU.86.86 and SMAD4-homozygously-deleted BxPC3." (PMID 28638102, 2017). "This is because vimentin can be expressed not only in pancreatic cancer cell but also in stromal fibroblasts." (PMID 28421110, 2017). "And our results also showed that N-cadherin and Vimentin mRNA levels were positively correlated with miR-23a expression in pancreatic cancer tissues." (PMID 29137308, 2017). "VEDT treatment inhibited the EMT induction by enhancing the expression of epithelial marker E-cadherin and decreasing the expression of mesenchymal markers N-cadherin and vimentin in pancreatic cancer cells and in tumor tissues." (PMID 28404939, 2017). "High expression of ZEB1 and vimentin, and low exprssion of E-cadherin, were verified in pancreatic cancer cell lines with intrinsic gemcitabine resistance, AsPC-1 and PANC-1." (PMID 28703793, 2017). "It has to be mentioned that the differential diagnosis between chronic pancreatitis and pancreatic cancer cannot be based on expression of vimentin." (PMID 28421110, 2017). "During EMT in tumour cells, up-regulation of vimentin and N-cadherin and down-regulation of E-cadherin (cell–cell adhesion molecules) promote cell invasion and metastasis in various cancers, including pancreatic cancer." (PMID 28077929, 2017). "Application of TLR4 siRNA and neutralizing antibodies against TLR4 and IL-10 expressed on M2-polarized TAM markedly inhibited E-cadherin reduction and the upregulation of Snail and vimentin in pancreatic cancer cells." (PMID 27191744, 2016). "DIM also decreased the expression of mesenchymal markers ZEB1, vimentin and Slug and changed the morphology of pancreatic cancer cells into the epithelial form." (PMID 27231938, 2016). "As a result, we found that HS-173 recovered the MET process as follows: the expression of Ecadherin was increased, whereas that of Vimentin was strongly decreased in TGF-β-induced pancreatic cancer cells." (PMID 27793006, 2016). "In human pancreatic tumour samples, fibronectin and vimentin are increased in high-grade tumours, with a corresponding decrease in E-cadherin expression." (PMID 27453691, 2016). "As expected, overexpression of miR-29a in pancreatic cancer cells increased expression of epithelial marker, E-cadherin and decreased mesenchymal marker, Vimentin." (PMID 27626694, 2016). "Western blot analysis showed up‐regulated pancreatic cancer mesenchymal marker vimentin and N‐cadherin and down‐regulated epithelial marker E‐cadherin in hypoxic conditions." (PMID 26395974, 2015). "In human pancreatic cancer, vimentin and fibronectin are up-regulated in high-grade tumors and within poorly differentiated areas of low-grade tumors, with a concurrent decrease in E-cadherin expression." (PMID 25593307, 2015). "We observed a Vimentin increase during pancreatic tumor progression in all 7 samples examined that were collected between 14 and 24 wpf (H′, H′′)." (PMID 24878567, 2014). "Examinations of tissue sections from pancreatic cancer patients revealed that pancreatic cancer cells near T-MSCs exhibit reduced E-cadherin expression and elevated vimentin expression." (PMID 24502410, 2014).
pancreatic cancer (continued). "PDAC cell lines were cultured with human recombinant BAFF, and morphology and gene expression were analyzed; pancreatic cancer cells changed to a fibroblast-like morphology, and showed altered gene expression of E-cadherin, vimentin and Snail." (PMID 23940742, 2013). "In vitro studies further confirmed the induction of EMT in pancreatic cancer cells by Wnt5a, as evidenced by increased expression of vimentin and reduced expression of E-cadherin." (PMID 24156409, 2013). "NFκB also promotes EMT in pancreatic cancer cells by inducing mesenchymal marker Vimentin and EMT-related transcriptional factor ZEB1." (PMID 22934011, 2012). "For example, gemcitabine-resistant pancreatic cancer cells display increased vimentin expression, and vimentin expression increased in Panc-1 cell lines when treated by TGFbeta." (PMID 21448168, 2011). "Vimentin expression by neoplastic cells was observed in 45% of the pancreatic adenocarcinomas and an expression level of >10% was noted in 27.5% of the pancreatic cancers." (PMID 21448168, 2011). "Reduction of VIM expression by siRNA decreased the invasion of Clone #3 revealing a role for VIM in pancreatic cancer cell invasion." (PMID 19216797, 2009). "Three novel proteins, ALDH1A1, STIP1 and VIM were chosen to validate and further investigate their involvement in pancreatic cancer invasion." (PMID 19216797, 2009). "Pancreatic tumor tissues showed greater than a 3-fold higher expression of total vimentin protein than did the lung, colon, and ovarian tumors that were analyzed." (PMID 18769604, 2006). "We have shown that a humoral response directed against a single isoform of vimentin occurred in 44.4% patients with pancreatic cancer." (PMID 18769604, 2006). "A similar pattern of expression was also observed in 6 pancreatic tumors, 38 lung tumors, 7 colon tumors and 25 ovarian tumors, suggesting that the major vimentin isoforms were ubiquitously expressed." (PMID 18769604, 2006). "Within, we report the identification of a vimentin isoform as an antigen that elicits a humoral immune response in pancreatic cancer." (PMID 18769604, 2006). "Autoantibodies were detected against a protein identified by mass spectrometry as vimentin, in sera from 16/36 patients with pancreatic cancer (44.4%)." (PMID 18769604, 2006). "For example, although increased levels of vimentin antibodies were found in pancreatic cancer, as compared to chronic pancreatitis and healthy individuals, the relationship between tumor burden, tumor staging and antibody levels needs further clarification." (PMID 18769604, 2006). "The major vimentin isoforms were present in the different cell lines examined, including 6 pancreatic tumor cell lines, 4 lung tumor cell lines, 9 colon tumor cell lines and 33 ovarian tumor cell lines, at similar expression levels." (PMID 18769604, 2006). "We analyzed (by Western blot) different tumor cell lines for the specific isoform of vimentin that was immunogenic in pancreatic tumor patients." (PMID 18769604, 2006). "Although the vimentin autoantibodies were largely restricted to patients with pancreatic cancer among the subject groups we investigated, further studies are needed to determine the specificity of the vimentin antibodies to pancreatic cancer." (PMID 18769604, 2006). "CaCO3@CM-OA treatment also increased the expression of Beclin 1 and LC3B/LC3A, indicating the activation of autophagy signaling pathway Detection of N-cadherin and Vimentin showed that CaCO3@CM-OA also inhibited the epithelial-mesenchymal transition (EMT) process of pancreatic cancer in vivo." (PMID 41377584, 2025). "Moreover, catechol has been identified to display anti-tumor efficacy and the ability to sensitize radio-resistant cells through the change of EMT markers such as vimentin, Snail, and E-cadherin in pancreatic cancer cells." (PMID 39796030, 2024). "Moreover, vimentin antibodies outperformed EpCAM antibodies in isolating CTCs from all pancreatic cancer patients." (PMID 37345161, 2023).
pancreatic cancer (continued). "MiR-138-5p possesses the ability to target vimentin and sensitize pancreatic cancer cells to 5-FU." (PMID 38139352, 2023). "We then used Western blot assay to look at the EMT markers (E-cadherin, N-cadherin, and vimentin) to see if SNAI2 could affect EMT in pancreatic cancer cells." (PMID 37251370, 2023). "Similarly, pancreatic tumors from other separate areas also expressed E-cadherin, pERK, and vimentin in the tumor stroma." (PMID 36650523, 2023). "Interestingly, a subset of patients exhibit autoantibodies to isoforms of vimentin, and their detection has been utilized for early diagnosis of pancreatic cancer." (PMID 37371811, 2023). "Furthermore, the IHC analysis showed that the decreased expression of CILP2 led to decreased levels of Ki-67, N-cadherin, and vimentin, as well as increased levels of E-cadherin in the orthotopic pancreatic cancer model." (PMID 38136386, 2023). "Furthermore, western blotting revealed that suppressing mTOR expression inhibits the progression of EMT in pancreatic cancer by downregulating the expression of N-cadherin and Vimentin but upregulating the expression of E-cadherin." (PMID 35449152, 2022). "Furthermore, miR-138-5p that can be downregulated by TGF-β also targets vimentin to enhance the chemosensitivity to 5-FU in pancreatic cancer." (PMID 33579377, 2021). "It was reported that propolis component caffeic acid phenethyl ester (CAPE) could inhibit the orthotopic growth and EMT of pancreatic cancer Panc-1 cells accompanied by the downregulation of vimentin and Twist 2 expression." (PMID 34068565, 2021). "It was reported that acquisition of vimentin expression and loss of E-cadherin expression during EMT results in tumor metastasis, invasion, radioresistance and generation of cancer cells with stem cell-like characteristics in pancreatic cancer." (PMID 33789624, 2021). "In summary, hsa-miR-143-3p may regulate KrasG12D, PI3K, ERK, JNK, p38MAPK, and vimentin synergistically to promote apoptosis and suppress cell growth, invasion, and migration in pancreatic cancer." (PMID 33643376, 2021). "In the present study, we found that overexpression of E-cadherin could enhance the sensitivity of pancreatic cancer cells to erlotinib possibly by regulating Twist and Vimentin expression." (PMID 34552882, 2021). "Moreover, knocking down K17 promoted epithelial-mesenchymal transition (EMT) in pancreatic cancer cell by inhibiting E-cadherin expression and inducing Vimentin expression, and the effects of K17 upregulation were opposite to that of K17downregulation." (PMID 33324659, 2020). "Moreover, similar research revealed higher expression of EMT-induced markers such as Vimentin and lower expression of E-cadherin in pancreatic cancer." (PMID 31684910, 2019). "Moreover, increased expression of UBL4A caused increased levels of LAMP1, LC3B, p62, and E-cadherin and resulted in decreased levels of CTSB, vimentin, and N-cadherin in the orthotopic pancreatic cancer models." (PMID 31288830, 2019). "Additionally, immunohistochemical results showed that the UBL4A level was positively correlated with the expression of LAMP1, LC3B, p62, and E-cadherin and negatively correlated with CTSB, vimentin, and N-cadherin in pancreatic cancer patients." (PMID 31288830, 2019). "Thus, expressions of Vimentin, Zeb1, and Snail were found to be downregulated upon rfhSP-D treatment in the pancreatic cancer cell lines." (PMID 30158928, 2018). "Consistent with the previous studies, our results showed that knockdown of YAP inhibited pancreatic cancer cell invasion, and this was accompanied by a dramatic reduction in the Vimentin and N-cadherin mRNA and protein levels, whereas both E-cadherin mRNA and protein levels were notably increased." (PMID 29587800, 2018). "In addition, ASIC1 and ASIC3 are positively correlated with expression of mesenchymal marker vimentin, but inversely correlated with epithelial marker E-cadherin in pancreatic cancer cells." (PMID 28518134, 2017).
pancreatic cancer (continued). "The results show that HNRNPA2B1 promotes EMT development by down-regulating E-cadherin and up-regulating N-cadherin and vimentin, and also stimulates the invasion capacity and inhibits viability in human pancreatic cancer cell lines, the similar results in vivo experiments." (PMID 28077929, 2017). "However, ectopic expression of TNC in pancreatic cancer cells resulted in downregulation of E-cadherin and upregulation of N-cadherin and Vimentin, as evidenced by western blot analysis and immunofluorescence assay." (PMID 29088796, 2017). "Furthermore, the immunofluorescence assay demonstrated that ASIC1 and ASIC3 positively correlated with the expression of mesenchymal marker Vimentin, inversely correlated with epithelial marker E-cadherin in human pancreatic cancer samples." (PMID 28518134, 2017). "Furthermore, we confirmed that lower HNRNPA2B1 expression corresponded with higher E-cadherin expression and lower N-cadherin and vimentin expression in pancreatic cancer cells." (PMID 28077929, 2017). "Accumulating experimental evidence suggests that many pancreatic cancer cell lines express higher levels of mesenchymal biomarkers, such as vimentin and N-cadherin, and lower levels of epithelial biomarkers, such as E-cadherin, than normal pancreatic cell lines." (PMID 28077929, 2017). "We found that ectopic expression of TNC in pancreatic cancer cells resulted in downregulation of the epithelial marker E-cadherin and concomitant downregulation of the mesenchymal markers N-cadherin and Vimentin, whereas SP600125 significantly reversed the TNC-induced change in EMT markers." (PMID 29088796, 2017). "Treatment with Cyt D has also been shown to reduce vimentin expression in pancreatic cancer cells." (PMID 25756282, 2015). "We have previously reported that DCLK1 is upregulated in pancreatic tumor tissues and co-localizes with vimentin, a marker of mesenchymal lineage within premalignant PanIN lesions, suggesting that these DCLK1+ cells are of mesenchymal origin or in the process of EMT." (PMID 25723399, 2015). "Indeed, prostate cancer epithelial cell line PC3 and pancreatic cancer epithelial cell line SU86.86 showed increased vimentin expression and enhanced migration ability with CDKL2 ectopic expression." (PMID 25333262, 2014). "Next, we analyzed the expression levels of EMT markers, including E-cadherin and vimentin, the major collagen receptor α2β1-integrin and the collagen uptake receptor Endo180 in the pancreatic cancer cell lines to clarify the relationship between EMT and collagen internalization." (PMID 22792318, 2012). "In 94 pancreatic cancers (27.5%), vimentin was expressed in >10% of neoplastic cells." (PMID 21448168, 2011). "Pancreatic cancer vimentin expression patterns have been investigated in small series." (PMID 21448168, 2011). "In addition, pancreatic cancer cell lines that express epithelial markers such as E-cadherin and lower levels of the mesenchymal marker vimentin are more responsive to erlotinib treatment." (PMID 20886123, 2010). "In addition, an unidentified specific vimentin isoform was found to elicit antibody production in pancreatic cancer." (PMID 20169076, 2010). "Further, we were unable to demonstrate aberrant N- or O-linked glycosylation of vimentin in the pancreatic tumor cell lines (data not shown)." (PMID 18769604, 2006). "We hypothesized that there might be changes in the expression level of the single minor antigenic isoform of vimentin that could lead to antigenicity in pancreatic cancer." (PMID 18769604, 2006). "Interestingly, although a number of vimentin isoforms were detected by monoclonal anti-vimentin antibody from Panc-1 whole cell lysates, only one vimentin isoform showed reactivity specifically with pancreatic cancer patient sera." (PMID 18769604, 2006). "The detection of autoantibodies to this specific isoform of vimentin may have utility for the early diagnosis of pancreatic cancer." (PMID 18769604, 2006).
pancreatic cancer (continued). "Although vimentin expression is approximately three fold higher in pancreatic tumors at the protein level, as compared to other tumors analyzed in our study, only a single isoform of vimentin had demonstrable immunogenicity to autoantibodies in pancreatic cancer patient’s sera." (PMID 18769604, 2006). "Thus, as the same peptide coverage was identified for each of the isoforms, we were unable to find evidence of protease cleavage leading to antigenicity of the specific vimentin isoform that was specifically reactive with pancreatic cancer patient’s serum." (PMID 18769604, 2006). "Moreover, vimentin antibodies outperformed EpCAM antibodies for all pancreatic cancer patients." (PMID 37345161, 2023). "Moreover, induction of TSPAN6 in human pancreatic cancer cells inhibits EGFR-induced expression of the EMT markers Vimentin and N-Cadherin, as well as the critical EMT transcription factor Slug, thereby linking TSPAN6 to the inhibition of EGFR-mediated EMT in human tumor cells." (PMID 35184157, 2022). "Higher expression of vimentin in pancreatic cancer cells may imply a higherstate of malignancy." (PMID 35107490, 2022). "However, it is still unknown if E-cadherin has any relevance in mediating Twist and Vimentin expression in pancreatic cancer." (PMID 34552882, 2021). "However, in the paraclone-derived pancreatic tumor similar expression patterns of Vimentin, N-cadherin, Integrin alpha V, CD44 and E-cadherin could be detected as in holoclone tumors." (PMID 30167093, 2018). "Furthermore and in accordance with the literature TGF-β treatment of control Panc-1 cells induced a time-dependent, significant downregulation of E-Cadherin expression and a concomitant induction of mesenchymal gene expression (SNAI2, VIM) in pancreatic cancer cells." (PMID 27713160, 2016). "Furthermore, TCGA data portal shows that human PDACs exhibit amplifications and mutations in ADAM10, MYC, VIM (vimentin), CD44, CCND1 (CyclinD1) and CTNNB1 (β-catenin), implying the importance of interfering with the signaling associated with these in prevention of pancreatic cancer." (PMID 26440150, 2015). "Inhibition of miR-210 expression decreased the expression of Vimentin and Snail-1 as well as cell migration, and increased the membrane-associated expression of β-catenin in Panc-1 cells co-cultured with PSCs indicating its role in regulating EMT and migration of the pancreatic cancer cells." (PMID 26029109, 2015). "Interestingly, the antigenic isoform of vimentin was expressed at 5–10 fold higher levels relative to the ubiquitous isoform in pancreatic tumors compared to other tumor types, and was expressed at approximately 50% higher levels than that found in normal pancreas." (PMID 18769604, 2006). "Initially, we determined the epithelial and/or mesenchymal states of the pancreatic cancer cell lines by assessing the expression of two extensively used markers, CDH1 and VIM, by ICC." (PMID 40531655, 2025). "The depletion of FOXP1 led to decreased mRNA and protein expression of N-cadherin and vimentin and increased expression of E-cadherin, underscoring the role of FOXP1 in regulating EMT and metastasis in chemoresistant pancreatic cancer." (PMID 40169859, 2025). "In the present study, we evaluated the expression of CDH1, VIM, EGFR, ERK1, ERK2, c-Jun, and c-Fos in 24 paired healthy and tumor tissues from pancreatic cancer patients who underwent resection surgery." (PMID 40305202, 2025). "Here, the expression of EMT-related proteins, E-cadherin, was downregulated, while N-cadherin, vimentin, and α-SMA were upregulated in pancreatic cancer cells treated with NETs." (PMID 40046958, 2025). "Immunohistochemical results of Ki67, Bcl2, Vimentin, and LC3A/B exhibit the same trend, demonstrating that CaCO3@CM-OA also exerted a good anti-pancreatic cancer effect in vivo." (PMID 41377584, 2025).